IL1B (interleukin 1 beta)
Diseases named in the same sentence as IL1B in open-access papers (continued):
Sharing a sentence is not in itself a finding about the gene and the disease.
cancer (continued). "IL-1β is located on chromosome 2q14 and its polymorphism and expression have been found to be associated with various cancers." (PMID 29312552, 2017). "The activation of inflammasomes has been documented in many human cancers and the role of inflammasome-related cytokines like IL-1β is also implicated in in vivo experiments." (PMID 28360909, 2017). "In other studies in patients with cancer, associations have been shown between appetite loss and IL-1β, IL-6 and IL-8 and with gene polymorphisms coding for TNF-α, IL-1β, and IL-10." (PMID 28542626, 2017). "EVs generated by cancer cells promoted the polarization of macrophages to an inflammatory phenotype, characterized by the upregulation of several M1-associated genes (IL-1β, IL-8, CCL2, CXCL2) and the downregulation of MRC1 expression, an M2-related marker." (PMID 28600520, 2017). "IL-1β and IL-18 are considered to be indicators of an increased risk of carcinoma and poor prognoses in multiple cancers." (PMID 28974683, 2017). "We assessed the ability of IL-1β to induce the expression of Vegfa in different cell types, including cancer-associated fibroblasts, endothelial cells, primary mammary adipocytes and primary BMDM." (PMID 27708283, 2016). "Inflammatory mediators such as IL-1β promote angiogenesis and overexpression of IL-1β mobilized myeloid-derived suppressor cells and induced gastric inflammation associated cancer." (PMID 27886105, 2016). "The proinflammatory cytokines, including TNF-α, IL-6, and IL-1β have been regarded as crucial factors causing cancer cachexia and muscle atrophy." (PMID 26600425, 2015). "IL-1β has a biphasic cancer-promoting effect on cancer metastasis, i.e. promoting cancer metastasis either by loss of IL-1β or by excessive IL-1β." (PMID 25706411, 2015). "Human carriers of IL-1B polymorphisms (IL-1B-511T and IL-1B-31C) show enhanced IL-1β production and increased circulating levels of the cytokine, resulting in an increased risk of cancers." (PMID 26176534, 2015). "Overexpression of the proinflammatory cytokine IL-1β is associated with diverse diseases, including cancer." (PMID 24571667, 2014). "Myeloid cells, including immature myeloid cells, neutrophils and macrophages, represent one of the most frequent immune cells associated with cancer and a cellular source for inflammasome activation and secretion of IL-1β and IL-18." (PMID 24474192, 2014). "In vitro, the inflammasome pathway and IL-1β were shown to increase macrophage chemotaxis and angiogenesis, both features linked to worse prognosis in various cancers." (PMID 24795727, 2014). "The present meta-analysis, including 91 high-quality case-control studies, is the most comprehensive meta-analysis to have evaluated the IL-1B polymorphisms (−511C/T and +3954C/T) and their relationship to cancer susceptibility." (PMID 23704929, 2013). "Recently, a meta-analysis of IL-1B –31T/C polymorphism and cancer risk has suggested that the –31C allele is a low-penetrance protective factor for the development of cancer." (PMID 23704929, 2013). "Our results demonstrated that IL-1B +3954C/T was significantly associated with increased overall cancer risk, especially among hospital-based case-control studies." (PMID 23704929, 2013). "First, IL-1β stimulates through the IL-1 receptor the NF-κB pathway, which is strongly associated with a variety of cancers." (PMID 24216700, 2013). "High plasma IL-1β levels are associated with a significantly increased risk of cancer, and tumor patients with high IL-1 expression have worse prognosis than those without." (PMID 23704929, 2013). "Association of the IL-1B +3954C/T polymorphism with cancer susceptibility: The analysis eventually included 26 case-control studies with 8083 cases and 9183 controls for IL-1B +3954C/T." (PMID 23704929, 2013).
cancer (continued). "Exposure of DCs to mafosfamide (MAFO)-treated cancer cells causes phenotypic maturation of DCs and their functional stimulation, characterized by the release of various cytokines (IL-1β, IL-6, IL-12)." (PMID 24376443, 2013). "In conclusion, this meta-analysis indicated that IL-1B +3954C/T was associated with significantly increased overall cancer risk, especially among hospital-based case-control studies." (PMID 23704929, 2013). "Pro-inflammatory IL-1 is implicated in cancer progression, and intratumoral levels of IL1β are higher compared with normal adjacent breast tissue." (PMID 23991131, 2013). "Summary odds ratios (ORs) and 95% confidence intervals (CIs) for the IL-1B −511C/T and +3954C/T polymorphisms and cancer risk were calculated." (PMID 23704929, 2013). "In this report, a meta-analysis was conducted to provide an overview of all the relevant studies and synthesize conclusions on the associations between the IL-1B –511C/T, +3954C/T polymorphisms and cancer susceptibility." (PMID 23704929, 2013). "IL-1β is a pleiotropic pro-inflammatory cytokine and its up-regulation is closely associated with various cancers including gastrointestinal tumors." (PMID 23174018, 2012). "The variable number of tandem repeats (VNTR) polymorphism in the second intron of the IL1 receptor antagonist gene (IL1-RN) and a polymorphism in exon 5 of IL1B (IL1B+3954C>T, rs1143634) have been suggested in predisposition to cancer risk." (PMID 23049925, 2012). "There has been literature reporting an association between inherited polymorphisms in the IL-1β gene and various cancers, including cervical, bladder and breast, but the results remain ambiguous." (PMID 22296757, 2012). "IL-1β has previously been implicated in peritoneal mesothelium integrity and in cancer cell dissemination." (PMID 22296757, 2012). "For example, TNF-α and IL-1β secreted from macrophages are not only essential in initiation of chronic inflammation, but also associated with the initiation of cancer by activating NF-κB signal pathway." (PMID 23227270, 2012). "The pooled results were affected by individual studies, therefore, more studies should be cumulated to evaluate the role of the IL1B+3954 polymorphism in the etiology of cancer." (PMID 23049925, 2012). "The increased expression of interleukin-1beta (IL-1β) in metastatic MFOC3 cells was of particular interest to us because it has previously been implicated in cancer cell dissemination." (PMID 22296757, 2012). "More studies are needed to further evaluate the role of the IL1B+3954 polymorphism in the etiology of cancer." (PMID 23049925, 2012). "Selumetinib has also been shown to inhibit secretion of cytokines such as IL-6, IL-1β and tumour necrosis factor-α, which are implicated in the promotion of cancer cachexia." (PMID 22510747, 2012). "Several IL1B gene single nucleotide polymorphisms have been described to be associated with cancers to date." (PMID 23049925, 2012). "Meta-analysis results revealed IL1B+3954 had a borderline significant association with increased cancer risk." (PMID 23049925, 2012). "Previously, we have reported the polymorphism in the promoter of IL1B(IL-1B -31T>C, rs1143627) was a low-penetrance protective factor for the development of cancer." (PMID 23049925, 2012). "Gene-cluster polymorphisms in the interleukin-1 (IL1B) are associated with an increased risk of gastric and other types of cancer." (PMID 19099590, 2008). "Interestingly, upregulated tumorigenic expression of Il1B has been associated with a worse prognosis in patients with cancer." (PMID 39305371, 2025). "Given the high levels of Vim and low levels of α-SMA, these cells may have an inflammatory phenotype similar to cancer-associated fibroblasts (CAFs) that differentiate under TNF-α + IL-1β stimulation." (PMID 39808504, 2025). "IL-1β and IL-18 are highly associated with cancer progression, and IL-1β might be related to immunotherapy resistance." (PMID 39762211, 2025).
cancer (continued). "IL-1β is another key player in the inflammatory milieu associated with cancer pain." (PMID 40579593, 2025). "Their findings revealed a HIF-1α/IL-1β signalling loop between cancer cells and tumour-associated macrophages in a hypoxic microenvironment, leading to epithelial–mesenchymal transition and cancer cell metastasis." (PMID 40264757, 2025). "Both IL-18 and IL-1β are implicated in promoting the tumorigenesis of various cancers." (PMID 40338411, 2025). "Fibroblasts might be necessary, too, as treatment of cancer-associated fibroblasts with IL-1β significantly enhanced their ability to inhibit CD8+ T cell function and proliferation, which was mediated by upregulation of PD-L1/2." (PMID 39796680, 2024). "Furthermore, obese individuals classically present higher levels of pro-inflammatory cytokines including IL-1β, which is associated with a variety of diseases including cancer." (PMID 39727499, 2024). "In addition, mutations in the IL1B gene have emerged as intriguing factors in the landscape of cancer development and progression." (PMID 38858637, 2024). "Given that TGF-β, IL-1β and IL-6 are essential for Th17 cell differentiation, the connection between neutrophilic asthma (characterized by high levels of these cytokines) and metabolic dysregulation and the risk of cancer becomes apparent." (PMID 38629073, 2024). "When inflammasomes like NLR family pyrin domain containing 3 (NLRP3) are activated, proinflammatory cytokines like interleukin-1 beta (IL-1β) and interleukin-18 (IL-18) are secreted, which can cause a persistent inflammatory state that worsens liver damage and accelerates the growth of cancer." (PMID 38780447, 2024). "Studies have shown that the A2A2 genotype is associated with elevated IL-1β levels, which could contribute to chronic inflammation, a key factor in cancer development." (PMID 39766795, 2024). "We hypothesize its role based on the high expression level of IL-1β within more invasive or aggressive cancer, as well as its association with survival." (PMID 38397123, 2024). "Several studies have demonstrated a relationship between genetic polymorphisms of interleukin‐1 beta (IL‐1β) and cancer development; however, their influence on cancer prognosis is unknown." (PMID 38798075, 2024). "On the other hand, IL-1β encodes interleukin-1β, a potent proinflammatory cytokine involved in the promotion of cell proliferation, angiogenesis, and the inhibition of apoptosis, all processes that facilitate cancer development and progression." (PMID 39766795, 2024). "The inflammatory mechanism is not specific to bacteria, in almost all mechanisms of bacterial inflammation and cancer, the implicated bacteria reside in the host for many years, accompanying this response to inflammation is the antiviral action of IL-1β, TNF-α and IFN-γ." (PMID 39608222, 2024). "In turn, metastasis of OC cells could be facilitated by the IL-1β/β1 integrin axis, and inflammation-associated cells transformed into cancer-associated immune cells that further developed OC proliferation, invasion, and metastasis." (PMID 37168255, 2023). "The heightened levels of IL-1β are associated with cancer progression." (PMID 36920652, 2023). "In addition, the secretome analysis of omental CM identified 157 cancer progression-associated proteins, with IL-6, IL-1β, and TGF-β as the key upstream mediators." (PMID 37554282, 2023). "Importantly, the inhibition of IL1β suppressed cancer cell migration and increased their susceptibility to chemotherapeutics." (PMID 35954425, 2022). "IL1B overexpression is associated with cancer development, metastasis, and poor prognosis in TNBC." (PMID 36474139, 2022). "IL‐1β is secreted by infiltrating neutrophils and induces IL‐6 production by intestinal mononuclear phagocytes, promoting tumorigenesis in colitis‐associated cancer mouse models." (PMID 35791509, 2022). "Both IL-1α and IL-1β participate in the systemic inflammation associated with cancer." (PMID 36072935, 2022).
cancer (continued). "Importantly, adding back IL-1β and GM-CSF to SIRPγ-deficient cancer cells rescued CD47 expression, leading to inhibition of phagocytosis by macrophages and restoration of tumorigenesis." (PMID 35229723, 2022). "IL-1β has been demonstrated as being a critical factor in this process and thus a key player in the loss of lean mass, appetite, and inflammatory upregulation, seen in cancer cachexia." (PMID 33907915, 2021). "In addition, IL-1β produced by cancer-associated fibroblasts (CAF) has also been described to favor the production of CCL22 by cancer cells in HNSCC." (PMID 33924428, 2021). "This meta-analysis showed that both the +3954C/T and IL-1β -511C/T polymorphisms might modulate cancer susceptibility." (PMID 33340075, 2021). "We speculate that in response to cancer-associated inflammation at the primary site, IL-1B is produced systemically and drives the mobilisation of immune cells from the bone marrow." (PMID 34290237, 2021). "Cancer cell-derived DAMPs (danger-associated molecular patterns), double-stranded oligodeoxynucleotides, or bacteria can be used to activate TLRs and the inflammasome to enable DCs to release IL-1β." (PMID 32635472, 2020). "Many human cancers express IL-1β and its overproduction is associated with poor prognosis." (PMID 32139737, 2020). "In addition, assembled inflammasomes can activate caspase-1 and cause IL-1β to be secreted from cancer cells." (PMID 32577124, 2020). "However, the consequences of IL-1β in WT or mutated BRCA1 on cancer initiation or progression remain to be investigated." (PMID 32635472, 2020). "In addition to cancer types, IL-1β can affect or can be affected by common cancer-associated mutations." (PMID 32635472, 2020). "With all these results, it is difficult to certify whether IL-1β expression or IL1B polymorphisms can predict the outcome of cancer patients." (PMID 32635472, 2020). "For example, evidence from our studies indicated that co-culturing of TNBC cells with mesenchymal stromal cells (MSCs) or cancer-associated fibroblasts (CAFs) in the presence of TNFα or IL-1β stimulation has given rise to contact-dependent increase in CXCL8, CCL2 and CCL5 levels in the co-cultures." (PMID 32605277, 2020). "The association of IL-1B rs2853550 with cancer risk has been discussed in several studies." (PMID 32527212, 2020). "As we have shown that KRAS causes NLRP3/IL-1β activation, targeting this axis may also be promising to achieve a therapeutic synergism with other anti-cancer therapies." (PMID 33116132, 2020). "Cancer cell stemness is often associated with drug resistance, thus we further studied whether IL-1β stimulation could increase the chemoresistance of SCC7 cells and B16-F10 cells." (PMID 32547321, 2020). "Anorexia in cancer patients is associated with the predominance of signals suppressing appetite in the hypothalamus—proopiomelanocortin and anorexigenic action of pro-inflammatory cytokines: IL-1α, IL-1β, IL-6, TNF-α." (PMID 33158194, 2020). "Interestingly, a study using the 4T1 cancer model has shown that IL-1β can cause immunosuppression in cancer by inhibiting activation of CD8+ T cells in parallel with PD1-mediated suppression." (PMID 32198421, 2020). "Cancer pain is closely associated with IKKβ/NF-κB, IL-1β, IL-6, and TNF-α." (PMID 32431607, 2020). "Overall, our results demonstrate that targeting IL-1β may attenuate cancer-associated thrombosis, particularly in cancer types that rely on increased G-CSF production and involvement of NET formation." (PMID 31552036, 2019). "IL-1β is a pleiotropic proinflammatory cytokine associated with diverse diseases, and accumulating evidence supports multifaceted roles of IL-1β in immune modulation and cancer progression." (PMID 30683126, 2019). "Overall, our results demonstrate that IL-1β might be a feasible target to attenuate cancer-associated thrombosis, particularly in cancer types that rely on increased G-CSF production and involvement of NET formation." (PMID 31552036, 2019).
cancer (continued). "One of the major similarities between mf- and cancer cell line- exposed monocytes is the significant upregulation in the mRNA levels of IL-1β (associated with inflammation or M1 phenotype), MMP9 (associated with angiogenesis), and TGM2 (associated with M2 phenotype)." (PMID 29668679, 2018). "Given that PC patients have the highest frequency of weight loss than those with other common cancers, our primary objective in this study was to explore the association of CC status with the serum IL-1β, IL-6, IL-8, or TNF-α levels in patients with resected or locally advanced PC." (PMID 30513776, 2018). "An association between cancer treatment-related symptoms and inflammatory cytokines could be shown, triggered by increased production and synergistic action of IL-1β and TNFα." (PMID 30042333, 2018). "Interleukin‐1β (IL‐1β) is a major cytokine involved in cancer‐associated chronic inflammation." (PMID 28599100, 2017). "Further, despite the absence of adaptive immunity, splenic tissue from orthotopically engrafted mice demonstrated elevations in several pro-inflammatory cytokines associated with cancer cachexia, including TNFα, IL1β, IL6 and KC (murine IL8 homologue), when compared to controls." (PMID 27901481, 2017). "In addition, inflammation is associated with cancer risk and development; there is evidence that a pro-inflammatory environment promotes activation of IL1B." (PMID 28225867, 2017). "High IL-1β secretion is associated with malignant phenotype in the cancer microenvironment, and IL-1β may promote the inflammatory cycle in the cancer microenvironment that induces sterile inflammation and carcinogenesis." (PMID 28865486, 2017). "Cancer-associated fibroblasts (CAFs) contribute to the malignant aggressiveness through secreted factors like IL1β, which may drive pro-tumorigenic inflammatory phenotypes mainly acting via the cognate receptor named IL1R1." (PMID 27072893, 2016). "Several lines of evidence suggests that in cancer the inflammasome is positively associated with characteristics such as elevated levels of IL-1β and IL-18, activation of NF-κB signaling, enhanced mitochondrial oxidative stress, and activation of autophagic process." (PMID 27206676, 2016). "As the pooled analysis for the association of IL‐1B −511 and +3954 polymorphisms with cancer risk have been performed elsewhere in May 2013 7, we only focused on IL‐1B 31 polymorphism in the present study." (PMID 26805397, 2016). "Polymorphisms of IL-1β are associated with increased cancer risk." (PMID 26896068, 2016). "As IL-1β has also been linked to the expression of other cancer-associated cytokines, we tested the impact of miR-7-5p or si-RelA on expression of IL-6 and IL-8, and found that both miR-7-5p and si-RelA reduced the levels of secreted and intracellular IL-6 and IL-8." (PMID 27203220, 2016). "Also, in advanced stages of cancer, IL-1β is strongly associated with loss of appetite, weight loss, sarcopenia, and general weakness." (PMID 26504362, 2015). "SNP rs16944 increases the expression of IL-1β, thus increasing the susceptibility of cancer." (PMID 25928231, 2015). "Since DJ-1 deficiency has been demonstrated to up-regulate IL-1β, lack or loss of DJ-1 might affect migration of cancer cells to lungs via the IL-1β-regulated MDSCs accumulation in the lung tissue." (PMID 25706411, 2015). "Stratification analyses of the IL-1B –511C/T polymorphism on cancer susceptibility." (PMID 23704929, 2013). "Some other factors may weaken the effect of IL-1B –511C/T on cancer risk in different ethnic groups." (PMID 23704929, 2013). "This meta-analysis suggested that both the IL-1B –511C/T and +3954C/T polymorphisms might modulate cancer susceptibility." (PMID 23704929, 2013). "The pooled results indicated that IL-1B +3954C/T (dominant model: OR = 1.15, 95% CI: 1.01–1.30) was significantly associated with increased overall cancer risk, especially among hospital-based case-control studies (dominant model: OR = 1.30, 95% CI: 1.02–1.66)." (PMID 23704929, 2013).